ANXA2 (annexin A2)
Diseases named in the same sentence as ANXA2 in open-access papers (continued):
Sharing a sentence is not in itself a finding about the gene and the disease.
hepatocellular carcinoma (continued). "Additionally, M. hyorhinis increases the resistance of hepatocellular carcinoma cells to certain nucleoside analogue chemotherapeutic drugs such as cisplatin, gemcitabine, and mitoxantrone through the interaction of p37 and Annexin A2." (PMID 37482693, 2023). "We speculate that S100A10 and ANXA2 may also activate the Akt/mTOR pathway in hepatocellular carcinoma." (PMID 37420211, 2023). "Moreover, S100A11/ANXA2 complex is overexpressed in stressed cells to maintain the integrity of the plasma membrane, which can be damaged by cancer cell migration in hepatocellular carcinoma (HCC)." (PMID 35752610, 2022). "Another study reported that ANXA2 was overexpressed in hepatoma cells compared to normal cells." (PMID 34575275, 2021). "Furthermore, knockdown of ANXA2 in a hepatoma cell line, MHCC97-H, repressed cell growth and invasive ability." (PMID 34575275, 2021). "ANXA2 was reported to prevent β-catenin phosphorylation and degradation by binding glycogen synthase kinase 3β (GSK3β) and disrupting the formation of the GSK3β/β-catenin complex in hepatocellular carcinoma cells." (PMID 31695775, 2019). "Annexin A2 is a discriminative serological candidate in early hepatocellular carcinoma." (PMID 30881525, 2019). "Over the period of 2014~ 2017, researchers pointed out that high expression of ANXA2 in biopsies of epithelial ovarian cancer (56.42%), urothelial carcinoma (53.02%), hepatocellular carcinoma (HCC; 73.81%), NPC (33%), and serous ovarian cancer (57.79%) was associated with poor OS." (PMID 29598816, 2018). "As over-expression of Annexin A2 was evident in human hepatoma, (20S)G-Rh2 might be a promising natural compound for targeted liver cancer therapy." (PMID 28963461, 2017). "ANXA2 promotes cell invasion in malignancies of the breast, brain, liver, and pancreas and enhances cell motility and cell adhesion of prostate and hepatocellular carcinoma cells." (PMID 27402115, 2016). "Previously, we reported that CD147 coprecipitates and colocalizes with Annexin A2 in hepatocellular carcinoma (HCC) cells and they may form a functional complex." (PMID 26716413, 2016). "Indeed, another study on hepatoma xenograft in mice demonstrated that the distribution of ANXA2 is mainly localized to the cell membrane in shRNA-bearing group." (PMID 25402728, 2015). "Annexin A2, a potential serum marker for hepatocellular carcinoma may play an important role in liver cancer progression." (PMID 24884814, 2014). "The objectives of the present study were to analyse ANXA2 expression and gene transcription in hepatoma cell lines and focus on the effects of silencing ANXA2 by small hairpin RNA (shRNA) on the proliferation and invasion ability of hepatoma cells with high metastatic potential in vitro and in vivo." (PMID 24348815, 2014). "Annexin A2 has been shown to promote cell invasion in malignancies of the breast, brain, liver, and pancreas and enhances cell motility and cell adhesion of prostate and hepatocellular carcinoma cells." (PMID 23945256, 2013). "In hepatocellular carcinoma (HCC), ANXA2 overexpression correlates with tumor aggressiveness and metastasis, influencing cancer progression by regulating the extracellular matrix and promoting tumor cell migration and invasion." (PMID 40018411, 2025). "ANXA2P2 is one of three pseudogenes of annexin A2 that have recently been shown to be aberrantly transcribed in hepatocellular carcinoma (HCC) cells." (PMID 33194647, 2020). "ANXA2P2 (annexin A2 pseudogene 2) is one of three pseudogenes of annexin A2 that have recently been shown to be aberrantly transcribed in hepatocellular carcinoma (HCC) cells." (PMID 30881525, 2019). "Thus, Annexin A2 might be an important target protein, and (20S)G-Rh2 is a promising natural compound for anti-hepatoma therapies." (PMID 28963461, 2017). "Hepatocyte Annexin A2 (ANXA2) expression is associated with the progression and metastasis of hepatocellular carcinoma (HCC)." (PMID 24348815, 2014).
hepatocellular carcinoma (continued). "In hepatocellular carcinoma (HCC), long non-coding RNA binds to ANXA2, enhances its protein stability, and promotes oxaliplatin resistance." (PMID 40069750, 2025). "Ubap2 reportedly forms a complex with Annexin A2 (ANXA2) and promotes its degradation via ubiquitination, resulting in the inhibition of hepatocellular carcinoma progression." (PMID 37339951, 2023). "The combination of annexin A2 and alpha-fetoprotein (AFP) improved the sensitivity in detecting early stage hepatocellular carcinoma." (PMID 33406648, 2021). "AnxA2 belongs to the calcium- and phospholipid-binding protein family of annexins and is a host cellular marker found aberrantly expressed in various malignant tumors (colon, lung, gastric, oesophageal, and breast) including hepatocellular carcinoma (HCC)." (PMID 29228983, 2017). "Despite the fact that AnxA2 does not have signals for its secretion, it was identified as a secretory biomarker for gastric cancer, oral squamous cell carcinoma, endometrial cancer and hepatocellular carcinoma." (PMID 33374917, 2020). "Notably, the expression levels of certain genes, such as ANXA2 and EZH2, were significantly elevated in HCC tumor tissues, further underscoring their importance in hepatocellular carcinoma development." (PMID 40018411, 2025). "The interaction between LINC01133 and ANXA2 had the highest score for protein identification analysis and was also identified with the RNA immunoprecipitation chip (RIP) assay in MHCC97H hepatocellular carcinoma (HCC) cells." (PMID 35747817, 2022). "However, this may not be representative for all human hepatocellular carcinoma cell lines as AnxA2 depletion in HepG2 cells, which express approximately 5-fold less AnxA2 mRNA compared to HuH7, did not alter PCSK9 or LDL-R protein expression." (PMID 28456096, 2017).
glioma (67 papers, 2009 to 2025). A benign or malignant brain and spinal cord tumor that arises from glial cells (astrocytes, oligodendrocytes, ependymal cells). "ANXA2 was associated with increased features of cancer in glioma cells, such as angiogenesis, migration, and invasion." (PMID 38639785, 2024). "In gliomas, annexin A2 is overexpressed and associated with a mesenchymal and invasive phenotype due to its interaction with transcription factors involved in the epithelial-mesenchymal transition (EMT), such as RUNX1, FOSL2, and BHLHB2." (PMID 35784465, 2022). "Amlexanox (Amx) inhibited the association between S100A13 and ANXA2 in C6 glioma cells cultured under serum-free conditions in the in situ proximity ligation assay." (PMID 33807671, 2021). "To investigate the biological signatures associated with ANXA2 in gliomas, we ranked the related genes based on Spearman’s correlation analysis (|R|> 0.6 and P < 0.05)." (PMID 34675316, 2021). "Previous studies reveal invasion function for ANXA2 in glioma and suggest its role as a potential diagnostic and prognostic marker for glioma." (PMID 30898167, 2019). "RNAi of annexin A2, a protein strongly implicated in glioma progression, prevented IL-1 induction, demonstrating its new role in innate immune activation." (PMID 25054228, 2014). "Our finding that annexin A2, a molecule strongly implicated in glioma progression by many studies, has a critical positive role in glioma IL-1 synthesis is also novel." (PMID 25054228, 2014). "A significant reduction of glioma tumor growth and progression in the annexin A2 knockout mice model associated with a decrease in cancer cell invasion, angiogenesis and proliferation has also been reported." (PMID 23945256, 2013). "Therefore, we analyzed the differences of ANXA2 in gliomas with different grades and IDH mutation types." (PMID 34675316, 2021). "In addition, high expression (> median level) of ANXA2 or OSMR was significantly associated with poor survival in the glioma patients." (PMID 32248843, 2020). "Annexin A2 has been implicated in driving glioma invasion and progression and has been demonstrated as one of the most abundant proteins in glioma EVs, but the functional role of transferring Annexin A2 via EVs in glioma progression has yet to be elucidated." (PMID 32038644, 2019). "Additionally, Kaplan–Meier analysis revealed that highly expressed ANXA2 and annexin A2 pseudogenes were associated with the poor survival outcome of glioma patients." (PMID 29291003, 2017). "Highly expressed ANXA2 and its pseudogenes were associated with poor survival, and could be the independent prognosis factors for glioma patients." (PMID 29291003, 2017). "Immunofluorescence labeling revealed robust upregulation of annexin-a2 protein expression in GBM versus normal brain as well as lower grade glioma samples." (PMID 41366031, 2025). "One study showed that increased levels of ANXA2 in samples of human glioma cells corresponded with increased severity of their disease." (PMID 38639785, 2024). "It has been shown that the expression of Glypican-1 is increased by Annexin A2 through a positive feedback loop with c-Myc that ultimately promotes glioma cell proliferation." (PMID 38272115, 2024). "Taken together, our study provided an explainable theory that ANXA2/NSUN2/YBX1 axis modulated the generation of B7‐H3 isoform in glioma cells." (PMID 39048916, 2024). "By mass spectrum, we noticed one RNA binding protein (RBP), annexin A2 (ANXA2) was found to interact with B7‐H3 transcripts in all glioma cells except U373MG." (PMID 39048916, 2024). "Our findings have uncovered a series of factors (ANXA2/NSUN2/YBX1) that can determine the alternative generation of different isoforms of B7‐H3 in glioma." (PMID 39048916, 2024). "By comparing among five glioma cells, we have finally found three proteins ANXA2/NSUN2/YBX1 that can explain the phenotypes in different cells." (PMID 39048916, 2024).
glioma (continued). "When C6 glioma cells were pretreated with various types of P4-ATPase siRNA, ANXA2 flop-out was significantly abolished only by ATP8A2 siRNA." (PMID 37371039, 2023). "ANXA2 is abnormally expressed in a variety of tumors, such as glioma, cervical cancer, LIHC, triple-negative breast cancer and nasopharyngeal carcinoma, and can serve as a prognostic marker in these tumors." (PMID 36713082, 2023). "The surface protein annexin A2, a calcium-binding cytoskeletal protein located at the extracellular surface of various tumor cell types, including glioma, is involved in tumor progression through cell migration and invasion." (PMID 37444498, 2023). "ANXA2 also accelerates the progression of various cancers; specifically, ANXA2 is highly expressed in GBM compared with that in low-grade glioma and promotes proliferation and invasion." (PMID 37834227, 2023). "The expression of both JAG1 and ANXA2 was higher in patients with high-grade glioma than in patients with grade II and III glioma and were positively correlated with each other." (PMID 37834227, 2023). "A recent study showed that overexpression of Annexin A2 (Anxa2) increased the expression of Glypican 1 (Gpc1) via c-Myc, creating a positive feedback loop that enhances proliferation of glioma cells." (PMID 35223842, 2022). "There are few comprehensive reports on the role of ANXA2 in glioma-related immune response based on large samples, which limits the development of clinically viable ANXA2-related therapies." (PMID 34675316, 2021). "After adjusting for the five clinicopathological factors (age, grade, IDH status, 1p/19q status and O6-methylguanine-DNA methyltransferase (MGMT) status), ANXA2 expression remained an independent prognostic factor for glioma patients." (PMID 34675316, 2021). "Our study revealed that ANXA2 is a biomarker closely related to the malignant phenotype and poor prognosis of glioma, and plays an important role in immune response, inflammatory activity and immunosuppression." (PMID 34675316, 2021). "Both mRNA and protein levels of ANXA2 were upregulated in glioma tissues and coincided with the overexpression of GPC1." (PMID 33712571, 2021). "Then, an association analysis was performed between ANXA2 and GPC1 expression and the clinicopathological features of glioma patients." (PMID 33712571, 2021). "In conclusion, ANXA2 promotes glioma cell proliferation by forming a positive feedback loop between GPC1 and c-Myc, indicating a potential and promising target for glioma treatment in future studies." (PMID 33712571, 2021). "The clinical application of ANXA2-targeted therapy, especially for gliomas, also needs to be further studied in more depth in the future." (PMID 34675316, 2021). "Both ProTα-EGFP release and ANXA2 externalization in C6 glioma cells were significantly inhibited by the addition of ω-conotoxin (ω-CTX) GVIA, an N-type voltage-dependent Ca2+ channel inhibitor." (PMID 33807671, 2021). "The knockdown of GPC1 significantly reversed the ANXA2-mediated proliferation of glioma cells and the upregulation of c-Myc." (PMID 33712571, 2021). "Further gene ontology analysis showed that ANXA2 was mainly involved in immune response and inflammatory activities of glioma." (PMID 34675316, 2021). "Knockdown of ANXA2 inhibited the proliferation of the glioma cell lines U251, U87, and GP137,38, primary glioma cells and glioblastoma stem-like cells." (PMID 33712571, 2021). "We aimed to reveal the role of ANXA2 in the malignant behavior of glioma comprehensively through conducting an analysis with large samples." (PMID 34675316, 2021). "We found that high expression of ANXA2 predicted malignant pathological subtypes of glioma and poor patient prognosis, and that ANXA2 expression was closely related to the glioma-related immune response, especially inflammatory activity and immunosuppression." (PMID 34675316, 2021).
glioma (continued). "In summary, this study comprehensively explored the expression pattern and biological function of ANXA2 in glioma through large samples." (PMID 34675316, 2021). "GO analysis showed that ANXA2 was involved in the glioma immune response, inflammatory response, neovascularization, fibrin decomposition and other processes." (PMID 34675316, 2021). "Conversely, glioma patients who expressed low levels of either ANXA2 or GPC1 had a better prognosis." (PMID 33712571, 2021). "In contrast, under serum-free conditions, ANXA2 externalization was observed at 3 h in control siRNA-treated C6 glioma cells." (PMID 33807671, 2021). "All the statistical analyses and figures were generated with R. ANXA2 was overexpressed significantly in high-grade glioma, isocitrate dehydrogenase wild-type and mesenchymal-subtype glioma." (PMID 34675316, 2021). "To determine the immune functions of ANXA2 in glioma, we downloaded immune system gene sets from the AmiGO 2 website." (PMID 34675316, 2021). "This study is the largest large-scale clinical study of ANXA2 in glioma thus far, and we comprehensively analyzed the expression pattern and related immune characteristics of ANXA2 and its clinical significance." (PMID 34675316, 2021). "Previous studies have suggested that ANXA2 is a crucial protein involved in the overproliferation of various human malignant tumor cells, including glioma cells." (PMID 33712571, 2021). "In our present study, we demonstrated that ANXA2 depletion significantly decreased the proliferation of human U118 glioma cells." (PMID 33712571, 2021). "We found that the expression level of ANXA2 increased with the degree of glioma, there was a statistically difference in the expression level of ANXA2 among different grades." (PMID 34675316, 2021). "In contrast, both Syt-1 and S100A13 remained in the C6 glioma cells cultured under serum-free conditions following anti-ANXA2 antibody delivery." (PMID 33807671, 2021). "Our results indicate that ANXA2 expression is significantly correlated with immune function in glioma." (PMID 34675316, 2021). "This study provides a powerful theoretical basis for the design of ANXA2-targeted therapeutics for glioma." (PMID 34675316, 2021). "Our results showed that ANXA2 plays an important role in the immunobiological processes of glioma patients." (PMID 34675316, 2021). "To investigate the effect of ANXA2 on glioma cell proliferation, we knocked down ANXA2 in U118 cells using two independent short-hairpin RNAs (shRNAs)." (PMID 33712571, 2021). "In contrast, irANXA2 was detected in both cases, suggesting that ANXA2 is externalized under serum-free conditions but remains on the outer surface of C6 glioma cells." (PMID 33807671, 2021). "We confirmed that ANXA2 can be used as a molecular marker for the clinical diagnosis of glioma and can be used to evaluate the prognosis and outcomes of glioma patients through large-scale clinical studies." (PMID 34675316, 2021). "We further confirmed that ANXA2 induced glioma cell proliferation in a c-Myc-dependent manner by using a specific c-Myc inhibitor." (PMID 33712571, 2021). "As shown by correlation analysis, glioma-derived ANXA2 expression was positively correlated with biomarker gene expression in all six immune cell types in the TCGA and CGGA datasets." (PMID 34675316, 2021). "Intracerebral inoculation of canine glioma cells into the brains of athymic rats showed that AnxA2 is present in clusters of tumor cells surrounding dilated tumor vessels." (PMID 32575495, 2020). "In support of this, GSEA of GSE4412 showed a positive association between expression of interleukin (IL) –6–JAK–STAT3 pathway signature genes and high ANXA2 or OSMR expression in human glioma specimens." (PMID 32248843, 2020). "In the REMBRANDT dataset, we found that ANXA2 and OSMR expression were associated with the histopathologic grade of glioma, and higher expression was observed in GBM than in lower grade glioma." (PMID 32248843, 2020).